Y_RNA (Y RNA )
Gene: Miscellaneous RNA gene on chromosome 14 (69,143,852 to 69,143,953, reverse strand). Ensembl gene ENSG00000206768.
Homologues: Orthologues: chimpanzee Y_RNA (99% identical), macaque Y_RNA (94% identical). Paralogues in human: Y_RNA (91% identical), Y_RNA (90% identical), RNY3 (89% identical), Y_RNA (89% identical), RNY3P1 (88% identical), Y_RNA (88% identical), Y_RNA (87% identical), Y_RNA (86% identical), RNY3P7 (85% identical), Y_RNA (85% identical), RNY3P11 (84% identical), RNY3P14 (84% identical), and 98 more.